IL6 (interleukin 6)
Diseases named in the same sentence as IL6 in open-access papers (continued):
Sharing a sentence is not in itself a finding about the gene and the disease.
esophageal cancer (continued). "In a mouse model of esophageal cancer, recruitment of MDSC was correlated with IL-6 levels and tumor invasiveness, IL-6 being shown to induce the MDSCs." (PMID 31885581, 2019). "While a previous study reported the STAT3 mediates PI3K/AKT activation upon interleukin-6 treatment, our study showed a decreased protein expression of phospho-p85, phospho-AKT, and phospho-STAT3 in esophageal cancer cells after CYT-Rx20 treatment." (PMID 27875549, 2016). "TGF-β, IL-6, and FGF produced by CAFs contribute to chemoresistance in esophageal cancer." (PMID 40136652, 2025). "TRIM29 has been reported to inhibit cytokine production, such as IL6, and TRIM29 knockdown markedly enhanced the production of these cytokines, which could activate STAT3 in multiple tumors, including esophageal cancer." (PMID 37365152, 2023). "In fact, IL-6 and MDSC levels predicted prognosis in patients with esophageal cancer." (PMID 31885581, 2019). "In the present study, decreased tumour-related antigen (CEA and SCC) and malignant biomarkers (IL-6 and MIC-1) expression at both mRNA and protein secretion levels in CMSP-treated cells indicated that oesophageal cancer cells lost the malignant phenotype gradually." (PMID 27501997, 2016). "To further investigate whether IL-6 was responsible for aggressive tumor growth in esophageal SCC, we suppressed IL-6 in esophageal cancer cells using a silencing vector." (PMID 23561329, 2013). "Although neither IL-6 mRNA levels in tumor tissues nor basal serum IL-6 levels correlated with sensitivity to radiotherapy in esophageal cancer patients, the percentage increase in serum IL-6 levels after radiotherapy was inversely correlated with tumor regression." (PMID 38114473, 2023). "A preclinical study on esophageal cancer showed that CAFs may block the infiltration of CD8+ T cells and increase the infiltration of CD4+ Treg through IL-6, and targeting CAFs can improve the existing tumor immunity and enhance the efficacy of conventional immunotherapy." (PMID 36685566, 2022). "CAFs might secrete IL-6 and remodel the immunosuppressive TME in esophageal cancer." (PMID 35966586, 2022). "Our data showed that 4NQO-induced IL-6 KO mice formed almost the same tumors as 4NQO-induced IL-6 WT mice, indicating that lack of IL-6 may not affect tumorigenesis of esophageal cancer." (PMID 34393797, 2021). "Therefore, targeting IL-6 signaling such as CK2 inhibitor and rapamycin could be a promising strategy for the treatment of esophageal cancer." (PMID 25238263, 2014). "IL-6 expression was higher in esophageal cancer specimens compared with non-malignant tissues." (PMID 23561329, 2013). "In addition, the analysis of gene expression profiles of patients with esophageal cancer identified ADAM12 as a noninflammatory-related serum marker for IL-6-producing CAFs, and serum levels of ADAM12 predicted unfavorable responses to neoadjuvant chemoradiation." (PMID 36572816, 2023). "Consistent with our finding that napabucasin sensitizes esophageal cancer cells to CRT, Ebbing and colleagues recently demonstrated that stroma cell-derived IL-6 mediates CRT resistance of esophageal adenocarcinomas, which could be reverted by inhibition of IL-6." (PMID 33530306, 2021).
metastatic disease (71 papers, 2002 to 2025). "Other studies have also described an association between higher IL-6 levels and poor survival in patients with metastatic disease, also influenced by chemotherapy resistance." (PMID 39342063, 2024). "Dysregulated IL-6 signaling is intrinsically linked to the stem-like and immunosuppressive features of the metastatic tumor." (PMID 33322216, 2020). "IL-6 levels are dramatically increased in metastatic diseases, and elevated levels of serum IL-6 are associated with poor disease outcome and prognosis in BC patients." (PMID 30154439, 2018). "According to some studies that evaluated clinical significance of IL-6 pre-treatment levels, IL-6 concentrations reflected disease status, and were commonly associated with metastatic disease." (PMID 20465852, 2010). "Importantly, some of these genes (THBS1, MAPKAPK2, CD9, TXNIP) were strongly associated with IL-6 signaling, indicating that IL-6 or its associated genes are coupled with metastatic tumors, in alignment with our previous findings." (PMID 34140316, 2021). "Similar studies also demonstrated that IL-6, a downstream mediator of the IL-1β, induced expansion of MDSCs, and IL-1 receptor (IL-1R)-deficient mice have a delayed accumulation of MDSCs and delayed primary and metastatic tumor progression." (PMID 33014771, 2020). "Thus, the decrease of FOSB in metastatic disease may cause divergence between TNFα and IL-6 PCa expression levels by changing the available ratios of the corresponding translated proteins for dimerization." (PMID 36371231, 2022). "Interestingly, several genes in this cluster or their homologs involved in angiogenesis and inhibition of apoptosis have previously been associated with metastatic tumor progression in murine SCC or human HNSCC (IL6, IL8, YAP1, and BIRC2), and shown to be regulated by NF-κB." (PMID 17498291, 2007). "A previous study revealed high expression of IL-6R in MDPs and demonstrated that metastatic tumors exhibiting elevated IL-6 levels prompted the differentiation of MDPs into M2-like macrophages." (PMID 40822347, 2025). "Several studies have demonstrated that pro-inflammatory cytokines such as IL-1β, IL-6 and IL-8 are higher in metastatic tumors and indicate poor survival in various cancer patients [34, -36]." (PMID 37501379, 2023). "Interleukin-6 (IL-6) is a cytokine that plays a role in controlling pro-inflammatory and metastatic tumors." (PMID 37631279, 2023). "To identify other factors possibly associated with IL-6 mediated effects on the tumor immune microenvironment (TME), we analyzed the top differentially expressed genes between localized vs. metastatic disease and evaluated their correlation with IL-6." (PMID 36371231, 2022). "We observed statistically significant opposing patterns of IL-6 and TNFα expression between localized and metastatic disease." (PMID 36371231, 2022). "We analyzed somatic tumor RNA-seq data for expression levels of TNFα and IL-6 in localized versus metastatic disease." (PMID 36371231, 2022). "In the clinic, anti-IL-6 studies were performed in patients with already advanced metastatic disease." (PMID 34140316, 2021). "Several clinical observations have documented increased IL-6 levels in plasma from patients with therapy-resistant metastatic disease compared to patients with earlier stages of the disease and healthy individuals." (PMID 33669522, 2021). "Two of the previously reported patients with IL-6 producing PPGL had metastatic disease, which originated from paraganglioma." (PMID 33715142, 2021). "The results showed that the protein levels of IL-1b and TNF-a in the hepatocyte co-culture+IL-6 treated LUADs derived metastatic tumor were dramatically elevated, whereas significantly decreased in the hepatocyte co-culture+Peptide 17 treated LUADs." (PMID 33495421, 2021).
metastatic disease (continued). "Epirubicin, although with much milder associated cardiotoxicity than other anthracyclines, is shown here to promote endothelial secretion of IL-6 and IL-8, previously linked to senescence and increased tumorigenesis, which in turn may be associated with increased risk of metastatic disease." (PMID 32974345, 2020). "In PC patients, IL-6 levels are higher in metastatic disease than in locally advanced tumors (p = 0.0001) and IL-6 released by myeloid cells in TME activates STAT3 signaling in PC cells, hence affecting poor patient’s outcome." (PMID 32012917, 2020). "Our results showed that cotreatment with DOX and T. pratense extract improved stereological parameters (i.e., reduction in the volume of metastatic tumors) in the lung and brain and decreased the serum levels of inflammatory cytokines (IL‐8 and IL‐6)." (PMID 33133558, 2020). "Circulating miR-21, IL-6, and IL-8 levels were measured at diagnosis of metastatic disease in both resectable and unresectable patient cohorts." (PMID 30636774, 2019). "To determine the ER/CD133/IL6 interplay in the development of HT-resistant metastatic disease, we generated an in vivo model of metastatic progression." (PMID 26858125, 2016). "The qRT-PCR analyses confirmed that the IL-1 and IL-6 expression levels and those of their corresponding receptors were increased in metastatic tumors." (PMID 27698389, 2016). "Significantly higher levels of the pro-osteoclastogenic cytokines IL-17F,RANKL, IL-1β, TNFα, and IL-6 were detected in the sera and supernatants fromLN-stimulated cells of animals bearing the metastatic tumors than in mice withnon-metastatic tumors." (PMID 23935856, 2013). "Separately, we have observed dramatically increased IL-6 expression in primary and metastatic tumors from mice with high metastatic rates (unpublished data), similar to the report that IL-6 promotes cancer cells to metastasize to distant sites." (PMID 24260500, 2013). "Serum IL-6 levels in patients with metastatic disease (9.3±7.8 pg ml−1) were higher than those in patients with localised disease (1.3±0.8 pg ml−1, P<0.001)." (PMID 15150588, 2004). "When results from the three groups of patients with cancer were individually compared with the controls and patients with BPH, IL-6 levels were significantly higher in patients with metastatic disease (mean 9.3±7.8 pg ml−1, median 7.0 pg ml−1, P<0.001)." (PMID 15150588, 2004). "Serum IL-6 was an independent prognostic factor in a multi-variate analysis in patients with metastatic disease." (PMID 11875705, 2002). "Biomarkers like IL-6, IL-8, IL-1β, and IL-11 offer opportunities for early detection, patient stratification, and personalized treatment approaches, enhancing the clinical management of metastatic disease." (PMID 39125732, 2024). "Pro-inflammatory interleukins such as IL-1, IL-6, and IL-8 facilitate osteoclastogenesis, tumor proliferation, and angiogenesis, thereby contributing to the complex interactions within the bone microenvironment that drive metastatic disease." (PMID 39125732, 2024). "IL-6 was robustly expressed in localized disease and downregulated in metastatic disease." (PMID 36371231, 2022). "Additionally, elevated levels of IL-1β and IL-6 have been detected in serum of mice bearing metastatic tumors." (PMID 33809315, 2021). "In 60 of the 84 (72%) patients with metastatic disease serum IL-6 was increased." (PMID 11875705, 2002). "The first is the capacity of Everolimus to restrain the progression of skeletal metastatic disease in BC patients through a specific mechanism that includes inhibiting the release by these cells of the most effective pro-OC factors such as M-CSF, TNFα, IL-1β, IL-6, MIP-1α and MMP-13." (PMID 26468083, 2015). "Thus indicating, as previously suggested, that IL-6 may act in metastatic tumor-bearing hosts as a CRH-independent pituitary stimulator." (PMID 23517603, 2013).
metastatic disease (continued). "The expression of IL-6, IL-6ST, and p-STAT3 (Tyr705) were significantly lower in FXR-silenced H1975 metastatic tumors than in corresponding control metastatic tumors." (PMID 38360812, 2024). "All models: Tumour size, growth and metastatic disease reduced with exercise.B16 and LLC – increased pro- and anti-inflammatory immune components including IL-6 and NK cells." (PMID 38149260, 2023). "We examined the upstream transcriptional factors (TFs) associated with TNFα and IL-6 regulation such as the Activator Protein 1 (AP-1) family of TF’s, NFkB and CEBP to decipher molecular mechanisms that may drive the differential expression of these cytokines in localized versus metastatic disease." (PMID 36371231, 2022). "By analyzing patient bulk RNA-seq data we observed that IL-6 and SELE expression are downregulated in metastatic disease, thus possibly contributing to an immunosuppressive effect." (PMID 36371231, 2022). "Thus, the postoperative increase seen in serum YKL-40 and IL-6 in some of the patients could be caused by micro-metastatic disease rather than the large surgical trauma in the liver, although it is possible that some effect of the surgical trauma persisted." (PMID 32756596, 2020). "Patients with metastatic disease had significantly higher VEGF and IL-6 levels than those with localized disease (P< 0.001)." (PMID 21546718, 2011). "Finally, as no serum acute-phase protein levels were assessed in this study, we cannot rule out that IL-6 serum levels in this population may merely be associated with a generalised inflammatory response to metastatic disease." (PMID 12771987, 2003). "Moreover, Z-GS also decreased the expression of FXR, IL-6, IL-6ST, and p-STAT3 (Tyr705) in FXR-overexpressed A549 metastatic tumors." (PMID 38360812, 2024). "Pituitary tumour stem cell marker expression has been associated with increased markers of proliferation, chemokines and cytokines, including IL-6, but not with clinically aggressive or metastatic disease, supporting a role in early tumourigenesis." (PMID 38483762, 2024). "Both IL-15 and IL-6 were elevated in patients with metastatic disease compared to patients with non-metastatic disease, as was identified via comparing levels in the first available serum sample across cohorts." (PMID 36831406, 2023). "IL-6 stimulates YKL-40 production, and in most types of cancer the proportion of patients with elevated plasma concentrations of YKL-40 is much higher in patients with metastatic disease than in patients with localized disease." (PMID 23840582, 2013). "Also, patients with metastatic disease had significantly higher VEGF and IL-6 levels than those with localized disease (all P < 0.001)." (PMID 21546718, 2011). "Analysing IL-6 in those patients with extensive disease elaborated about two-fold higher arterial IL-6 levels (13.42±17.4 pg ml−1) than respectively encountered in those patients without metastatic disease (7.06±9.8 pg ml−1)." (PMID 12454774, 2002). "Moreover, although the continuous blockade of macrophages constrains tumor progression, cessation of the CCL2 blocking therapy stimulates them to a rapid rebound, leading to accelerated metastatic disease via a mechanism dependent on VEGF-A and IL-6 production monocyte-derived by macrophages." (PMID 31447834, 2019). "Furthermore, IL-6 levels were associated with OS and EFS in STS patients with no metastatic disease at initial presentation." (PMID 28851899, 2017). "However, in preclinical models of wide metastatic disease, IL6 inhibitors do not lead to disease regression." (PMID 27163161, 2016). "However, in our study IL-6 was not able to differentiate advanced stages with metastasis from non-metastatic diseases." (PMID 26148092, 2015). "They suggested that in the absence of advanced metastatic disease, IL-6 levels may be used as an adverse prognostic marker." (PMID 20465852, 2010).
metastatic disease (continued). "We could not find any correlation between serum IL-6 and platelet numbers nor between serum IL-6 and VEGF levels, and this result was maintained when the analysis was restricted to patients who had not received any chemotherapy for their metastatic disease." (PMID 12771987, 2003).
gastric ulcer (70 papers, 2007 to 2025). An ulcerated lesion in the mucosal surface of the stomach. "Previous studies have indicated associations between ethanol-induced gastric ulcer elevations in inflammatory cytokines, such as interleukin-1β (IL-1β), interleukin-6 (IL-6), heme oxygenase-1 (HO-1), and tumor necrosis factor-α (TNF-α)." (PMID 39064740, 2024). "Several studies show a positive correlation between the severity of gastric ulcer and the increase in pro-inflammatory cytokines (IL-1β, IL-6, and TNF-α), associated with a reduction in anti-inflammatory cytokines (IL-10), influencing inflammatory scores." (PMID 33233494, 2020). "Proinflammatory cytokines, particularly TNF-α, IL-1β and IL-6, are closely associated with the degree of mucosal damage in gastric ulcer." (PMID 32871094, 2020). "It has been reported that H. pylori infection is associated with overexpression of IL-6 at the margin of gastric ulcer by macrophages." (PMID 31065302, 2019). "IL-6 stimulates the lymphocytes, macrophages, and neutrophils at the inflammation site, which leads to the excessive production of ROS and lysosomal enzymes, which in turn cause tissue damage in gastric ulcers." (PMID 33530540, 2021). "The impaired healing of gastric ulcer in diabetic rats was associated with suppressed tissue expression endothelial cell markers (i.e. eNOS and peNOS), enhanced pro-inflammatory reactions (i.e. IL-1β, IL-6 and myeloperoxidase activity) and reduced regenerative activity (i.e. MMP-2, IL-10 and cAMP)." (PMID 29095895, 2017). "The pro-inflammatory cytokines TNF-α and IL-6 played a vital role in promoting neutrophil infiltration into inflamed areas of the stomach and hindering the healing of gastric ulcers." (PMID 40775122, 2025). "ELISA showed that the expression of IL-1β and IL-6 in the serum increased following ethanol-mediated induction of gastric ulcers, and this increase was significantly inhibited by treatment with YWS at 300 mg/kg." (PMID 39861107, 2025). "Taken together, this study is the first to highlight the role of Apium graveolens L. in indomethacin-induced gastric ulcer, and correlate it to IKκB/NF-κB p65/IL1β, IL-6, TNF-α/iNOS signaling pathways." (PMID 38355510, 2024). "Apart from causing damage to the gastric mucosa, alcohol-induced gastric ulcers also prompt the onset of an acute inflammatory response and modify the concentrations of cellular inflammatory factors such as TNF-α, and IL-6." (PMID 38259271, 2023). "A separate study of a rat model of gastric ulcers reported that IND prompted an extensive inflammatory response with upregulated levels of both IL-6 and TNF-α." (PMID 37895164, 2023). "The inflammatory response caused by gastric mucosal injury increases the expression of inflammatory cytokines including TNF-α, IL-1β, and IL-6, and further triggers neutrophil infiltration and epithelial cell apoptosis, delaying the healing of gastric ulcers." (PMID 36552666, 2022). "Excessive secretion of IL-6 can activate neutrophils to form inflammatory sites, thus activating oxidative stress and lysosomal enzymes, leading to gastric mucosal damage and gastric ulcer." (PMID 34159200, 2021). "Pretreatment with AAEs significantly reduced the proinflammatory cytokine levels of IL-1β and IL-6 and enhanced the anti-inflammatory cytokine IL-10 in the gastric ulcer mice, suggesting that they provide protection against the inflammation of gastric ulcer." (PMID 34580595, 2021). "Studies have shown that pro-inflammatory cytokines, such as TNF-α, IL-1β, and IL-6 play important roles in the formation of gastric ulcers." (PMID 33233494, 2020). "Oral treatment with L-menthol decreased tumor necrosis factor-α (TNF-α), interleukin-6 (IL-6) levels, and increased interleukin-10 (IL-10) level in the rat model of gastric ulcers." (PMID 31827561, 2019).